GZMB (granzyme B)
Diseases named in the same sentence as GZMB in open-access papers (continued):
Sharing a sentence is not in itself a finding about the gene and the disease.
melanoma (continued). "In vivo, PTPN2 inhibitor cotreatment significantly reduced melanoma and colorectal tumor growth and enhanced mouse survival compared with anti-PD-1 treatment alone, and this was accompanied by increased tumor infiltration by granzyme B+ CD8+ T cells." (PMID 36968224, 2023). "Consistent with the metabolic alterations, PD1-deficient T-bet+NK1.1− ILCs have been characterized by an increased expression of IFN-γ and granzyme B and K. In addition, the presence of PD1-deficient T-bet+NK1.1− ILCs has been associated with inhibited growth of melanomas in mice." (PMID 37868977, 2023). "Additionally, significant differences of GZMB expressions were found in gender, and melanoma Clark level (P < 0.05)." (PMID 36443341, 2022). "Therefore, the same group developed an analogous biotinylated probe for human granzyme B by changing one amino acid of the tetrapeptide to create hGZP, which showed high specificity to human granzyme B in human melanoma biopsies." (PMID 35625811, 2022). "Immunohistochemical staining and in vivo imaging, using positron emission tomography (PET), of intratumoral granzyme B may serve as a predictive biomarker for PD-1 blockade in melanoma." (PMID 35514996, 2022). "Additionally, a patient with melanoma who showed a good response to treatment leading to the blockade of PD-1 showed increased mRNA expression of granzyme B and IFN-γ in the regressing tumor lesions." (PMID 34944392, 2021). "Furthermore, circulating NK cells from patients with advanced melanoma exhibited reduced expression of activating receptors, GzmB, and perforin when compared with HD blood NK cells." (PMID 34187852, 2021). "Moreover, we analyzed the expression level of gene CD3E, CD4, CD8A, GZMB, NKG7, TCF7 and TRBC2, the well-known markers for CD8+ T cells, and they were all shown to have significantly higher expression level in melanoma patients with low risk." (PMID 34040608, 2021). "Inter-tumoral delivery of mTORC2-deficient DCs (Rictor−/− DCs) showed pro-inflammatory properties and was associated with reduced melanoma tumor growth, increased numbers of INF-γ+ and granzyme B+ (GrB+) CD8+ TILs, and reduced frequency of immunosuppressive MDSCs within TME." (PMID 35250965, 2021). "Distance analysis carried out in patients based on their status at the last follow-up time point, revealed that alive patients (n = 11) had a higher frequency of melanoma cells within a 30 μm radius from CD8 + Granzyme B+ CTL, in comparison to dead patients (n = 10)." (PMID 33947438, 2021). "In addition, Th9 cells can also directly kill tumor cells by secreting granzyme B. Pharmacological inhibition of granzyme B activity significantly attenuates the cytotoxic activity of Th9 cells against B16F10 melanoma cells." (PMID 34944921, 2021). "Interestingly, we observed that in GBM, immune neighbor number is negatively correlated with CD8 and GZMB, whereas in melanoma (ipi-nivo), immune neighbor number is positively correlated with CD8." (PMID 34188042, 2021). "Importantly, Pmel-1 x SLAMF6 -/- T cells produced higher levels of granzyme B in response to melanoma compared to Pmel-1 T cells, which are already strong killers due to their TCR design." (PMID 32122464, 2020). "In addition, exosomal PD-L1 inhibits the proliferation of CD8+ T cells, as reflected by decreased expression levels of Ki-67 and Granzyme B, which promotes the progression of melanoma both in vivo and in vitro." (PMID 32391259, 2020). "Identification of activated T cells that might have contacted tumors characterized by circulating neoantigen-specific granzyme B+ PD-1+ T cells in melanoma and a similar pool in lung cancer albeit antigen-specificity was not assessed in this case." (PMID 32580514, 2020). "Ptgs+/+ melanoma cells grew progressively in either single germline EP2-deficient or conditional EP4-deficient mice, suggesting the dual deletion of both PGE2 receptors on granzyme B+ cells was required for spontaneous tumor regression." (PMID 33220234, 2020).
melanoma (continued). "In vitro exposure of melanoma cells to melphalan triggered a pronounced induction of expanded functional CD8+ T cells that produced high levels of granzyme B, perforin, and IFN-γ and also degranulated in the presence of melanoma target cells in a cytotoxicity assay." (PMID 30560089, 2018). "Moreover, conditioned media from M2-BCG vs. M2 elevated the frequency of granzyme B-producing CD8+ tumor-infiltrating lymphocytes (TILs) facing autologous melanoma cell lines (p < 0.01)." (PMID 28848560, 2017). "In accordance with the CD107a mobilization results, intracellular FACS analysis carried out on Vγ9Vδ2 T cells from 4 patients after melanoma removal revealed increased expression of perforin (70.3 ± 8,6% versus 25.3 ± 6.1%) and granzyme B (79.5 ± 10.4% versus 28.7 ± 6.7%)." (PMID 26915072, 2016). "Furthermore, adoptive transfer of STZ-diabetic P14 CD8+ effector cells showed an insufficient recruitment to the B16.gp33 melanoma and inadequate production of perforin, granzyme B and TNFα determined by immunohistochemistry in the tumor milieu." (PMID 25390652, 2014). "Moreover, levels of granzyme B in melanoma tissue were elevated in mice adoptively transferred with Cl-IB-MECA-treated CD8+ T cells compared with those injected with untreated CD8+ T cells or PBS." (PMID 23028986, 2012). "However, in melanomas, the presence of CD8+ T lymphocytes associated with granzyme B positivity was greater in more advanced stages of the disease and, additionally, these cells were positively associated with the expression of PDL-1 and IDO in the tumor stroma." (PMID 38913547, 2024). "Increased expression of CD8+ granzyme B+ T cells has been correlated with higher transcript levels of CCL17, and higher serum levels of CCL17 were also associated with progression-free survival in advanced melanoma patients undergoing dendritic-cell-based immunotherapy." (PMID 37762335, 2023). "Importantly, the results showed that compared with IgG2a treatments, PD-1 blockade therapies significantly reversed SPHK1- or MTA3-associated immune dysfunctions and enhanced the immune response against tumor cells, as reflected by the frequencies of CD8+ and GZMB+CD8+ T lymphocytes in melanoma." (PMID 36050478, 2022). "In conventional melanomas, granzyme B‐positive cytotoxic T lymphocytes constitute 1–10% of the inflammatory infiltrate and are believed to be involved in tumour cell killing through apoptosis induction, which may ultimately result in melanoma regression." (PMID 32970867, 2021). "Thus, NK cells infiltrate advanced melanoma environments and exhibit a reduced cytotoxic potential with decreased expression of GzmB and perforin, a defect that could be addressed by adoptive NK-cell therapies." (PMID 34187852, 2021). "In a third approach aiming at defining whether a defective transmission of lytic enzymes might occur at the CTL/melanoma cell synapse, we visualized granzyme B (GrzB) staining in target cells 15 min after conjugation with CTL using confocal laser scanning microscopy." (PMID 26940455, 2016). "Tebentafusp-dependent release of GZMB and IFN-γ was observed in cocultures with NHEMs, with a more pronounced effect in gp100-positive melanoma cells." (PMID 40311102, 2025). "Mi-2β mRNA levels negatively correlated with both GZMB and PRF1 mRNA expression (p < 0.01) in melanoma." (PMID 38461299, 2024). "The heatmap displayed that melanomas with high IRE1α activity have increased expressions of TIL signature molecules like IFNG, GZMB, CD8A and CXCL10." (PMID 38291473, 2024). "Increased expression of GZMB, CD69, IFN-γ, CD25 or CD107 in CD8+ T cells was detected in BRafV600E/Ptennull melanomas, and their induction was further augmented by the anti-PD-1 treatment." (PMID 38461299, 2024). "In the second experiment, we tested EpCAM-CAR-T cells co-cultured with EpCAM+ gastric PDXO-GA0091 and EpCAM- melanoma PDXO-ME1154, and measured the interferon-gamma and Granzyme B levels in the culture." (PMID 36602988, 2023).
melanoma (continued). "Using mouse melanoma as a model, NK cells exhibited higher expression of IFN-γ and granzyme B in tumors with reduced lactic acid production compared to control tumors." (PMID 37868977, 2023). "In a melanoma model treated with adoptive cell transfer (ACT), Th1 cytotoxic T cells differentiated from naïve CD4+ T cells secreted granzyme B, perforin and IFN‐γ, and expressed the transcription factor T‐bet." (PMID 37829505, 2023). "Investigations have shown that miR-155 is involved in the functions of NK cells in melanoma by positively regulating Killer Cell Lectin Like Receptor K1 (KLRK1), interferon (IFN-γ), and granzyme B production." (PMID 36980512, 2023). "The percentages of granzyme B-, perforin-, IFN-γ-positive CD8+ T cells in melanoma were also significantly increased to 53.1%, 49.5% and 34.9% of CD8+ T cells by NPTyr-C9AP treatment when compared to anti-PD-L1 group." (PMID 37031188, 2023). "Compared to nevus and normal samples, significant higher expressions of GZMB, C1QA, and C1QB were observed in primary melanoma and metastatic melanoma in GSE46517." (PMID 36443341, 2022). "Average values for each biomarker were higher in the disease control versus disease progression subgroups of patients for both melanoma and NSCLC cohorts, but P values were >0.05 in all comparisons except for granzyme B plus perforin in NSCLC (P = 0.03)." (PMID 35983060, 2022). "In melanoma cells, Beclin-1 inhibition prevented Granzyme B degradation and increased NK cell infiltration in a CCL5-dependent manner, thereby inhibiting melanoma growth." (PMID 36009363, 2022). "Compared to PBS control or sEVS345A, treatment with sEVWT and sEVS345D from both human and mouse melanoma cell lines significantly inhibited CD8+ T cell proliferation and activation, as assessed by their expression of Ki-67 and Granzyme B." (PMID 35835783, 2022). "CTLs bind to melanoma cells via TAA presented on MHC molecules and then exert an antitumor effect on melanoma cells by releasing perforin and granzyme B to induce apoptosis and secreting cytokines such as IFN-γ and TNF to reinforce the inflammatory TME." (PMID 36003368, 2022). "Of the proteins that were measured across all three tumor datasets, we observed that CD4, CD45RO, GZMB, Ki67, PTEN, Bcl-2, CD19/20, and Pan-CK are positively correlated with CD8 in GBM and in at least one melanoma treatment arm." (PMID 34188042, 2021). "In contrast, melanoma tissue showed a massive accumulation of CD68-positive immune cells, many proliferating cells and an increased immunoreactivity for granzyme-B and α-SMA." (PMID 34544377, 2021). "Anti-VEGF treatment of mouse models of melanoma significantly increased CD8+ T-cell numbers as well as their IFN-γ production, granzyme B release and perforin gene expression within the TME." (PMID 34944851, 2021). "In the adoptive cell therapy (ACT) setting, melanoma-specific TCR transgenic CD4+ T cells produced both IFN-γ and GzmB within tumors, suggesting that these cells have both helper and cytotoxic activities (Th-ctx)." (PMID 31924474, 2020). "All phenotypic and functional markers of T cells—CD3E, CD4, CD8B, FOXP3, GZMB, PRF1 and TBX21—were expressed at higher levels in melanoma patients with high ETV7 expression." (PMID 33424867, 2020). "Exosomes secreted from melanoma and NSCLC cells that express endogenous PD-L1 inhibit the expression of granzyme B (GzmB) from human peripheral and mouse splenic CD8+ T cells activated by TCR stimulation." (PMID 33178688, 2020). "We observed strong Pearson correlation coefficients between IL32 expression, found within the melanoma tumor and the surrounding microenvironment, and genes related to immune cell infiltration, such as CD3E (0.94), CD8A (0.89), IFNγ (0.75), and GZMB (0.86)." (PMID 30953519, 2019). "To study the tumor promoting properties of perforin and GzmB expressing MDSCs, we first performed an in vivo assay, evaluating the growth and metastasis of B16F10 cells, an aggressive melanoma tumor model." (PMID 31212684, 2019).
melanoma (continued). "In melanoma mice models, IMQ alone reduced tumor lesions through production of IFNα/β, which led to TRAIL and granzyme B secretion by pDCs, opposing the possible immunosuppressive effect of granzyme B expression in pDCs." (PMID 30987228, 2019). "Increased CD8+ T-cell infiltration/proliferation, PD-1, PD-L1, granzyme B, and phosphorylated STAT1 positive immune cells in melanoma tumors have been observed by IHC or gene expression after treatment with pembrolizumab or nivolumab in other trials." (PMID 31439037, 2019). "In a TCR-transgenic B16 melanoma model, MHCIIPOS melanoma cells are directly killed by cytotoxic CD4+ T cells in a perforin/granzyme B-dependent manner." (PMID 24782871, 2014). "Consistent with the increased granzyme B staining in vivo, L1S significantly enhanced the cytolytic activity of NWNA splenocytes against NK cell-sensitive B16F10 melanoma target cells in vitro." (PMID 22072975, 2011). "NK-exos typically contain cytotoxic proteins (e.g., granzyme B, perforin, FasL, and TRAIL), originating from NK cells, which exert potent tumor-killing effects against various cancers (e.g., melanoma, breast cancer, neuroblastoma, lung cancer, pancreatic cancer, and liver cancer)." (PMID 40076856, 2025). "Similarly, GZMB and GZMK were most strongly correlated with melanoma, underscoring the relevance of these genes in mediating anti-tumor immune responses in this cancer type." (PMID 40002821, 2025). "Moreover, an increase of GZMB expression and upregulation of CD8+ T-cell activation markers, such as CD69, IFN-γ, CD25 and CD107, were detected in BRafV600E/Ptennull/Mi-2βnull melanomas after Mi-2β knockout." (PMID 38461299, 2024). "Melanomas of Atg5BECKO mice, compared to those of WT mice, displayed an increased amount of both CD8+ T and CD4+ T‐cells and harbored CD8+ T‐cells with higher expression of the key effector molecule Granzyme B (GrzB)." (PMID 38009521, 2023). "As in melanoma was shown intracellular granzyme B levels in CD8+ T cells were decreased considerably in the presence of the melanoma-activated fibroblast secretome, while IFN-γ release was not affected." (PMID 36275750, 2022). "Finally, zDCs were also superior in their capacity to induce melanoma-specific CD8+ T cells, CD8+ T cell proliferation, and cytotoxic T cells, which produced approximately two times more IFN-γ and more granzyme B, than those stimulated with αDCs." (PMID 35269457, 2022). "Furthermore, immune cell–cell interaction is negatively correlated with CD8 and GZMB in GBM, but positively correlated with CD8 in melanoma (ipi-nivo arm)." (PMID 34188042, 2021). "For a mixed population of GZMB+ and GZMK+ CD4+ in melanoma, higher RUNX3 and PRDM1 (BLIMP-1) expression was predominant over low-level TBX21/EOMES expression, and the PRDM1 overexpression is supported by similar findings from GZMB+ CD4+ T cells in murine adenoviral infection." (PMID 34910940, 2021). "Accordingly, we observed the expression of Prf1 and Gzmb, encoding the CD8 T cell derived cytotoxic perforin 1 and granzyme B, only in NRF2 knockout, but not in control melanomas." (PMID 32978520, 2020). "Furthermore, siRNA reduction of Rasal1 expression in T-cells shrinks B16 melanoma and EL-4 lymphoma tumors, concurrent with an increase in CD8 + tumor-infiltrating T-cells expressing granzyme B and interferon γ-1." (PMID 31641113, 2019). "Furthermore, recovered CD8+ T cells from the melphalan-exposed melanoma co-culture produced significantly higher levels of IFN-γ and showed elevated intracellular levels of granzyme B and perforin." (PMID 30560089, 2018). "Co-culture with melanoma MCTS, resulted in defective TAA recognition by CTL as compared to 2D as witnessed by decreased IFN-γ production and decreased Fas Ligand, perforin and granzyme B gene expression." (PMID 17342088, 2007).
melanoma (continued). "In the case of 1H3 T-cells, destruction of A02 melanoma cells was mediated almost exclusively via the perforin/granzyme-B system, either in the presence or absence of the Bcl-2 inhibitor." (PMID 17311012, 2007). "Thus, we also assessed CTL functions by evaluating FasL, granzyme B, and perforin gene expression in CTL co-cultured with melanoma target cells growing in 2D or in MCTS." (PMID 17342088, 2007). "Many recent studies have reported that NK-exos may enhance tumor-targeting and anti-tumor activity by upregulating cytotoxic proteins (e.g., perforin, granzyme B, FasL, TRAIL, and caspases) in various cancers (e.g., melanoma, neuroblastoma, breast cancer, lung cancer, and pancreatic cancer)." (PMID 40076856, 2025). "Tebentafusp’s mechanism—redirecting polyclonal T cells to gp100-expressing melanoma cells—triggers robust immune activation, as demonstrated by skin biopsies showing infiltration of CD8+ cytotoxic T cells, upregulation of interferon-γ (IFN-γ), and granzyme B in cutaneous lesions." (PMID 41170451, 2025). "Accordingly, we observed that the T cell clones exposed to EVs-VSV secreted higher amounts of granzyme-B compared with T cells exposed to EVs from uninfected melanoma cells and a slight—although not significant—increase in the surface expression of the degranulation marker CD107a." (PMID 39492948, 2024). "Consistently, a correlation matrix profiling of gene mRNA expression in TCGA collection of melanoma tumors showed that CD40 expression significantly and positively correlates with CD4 and CD8 infiltrates, as well as with type 1 cytokine responses based on IFNγ and GzmB expression patterns." (PMID 34092233, 2021). "Similarly, CD56dimCD16+ NK cells also exhibited reduced DNAM1 as well as GzmB and perforin expression while modest changes in the activating receptors NKG2D and NKp46 expression were found in CD56dimCD16− NK cells from advanced melanoma compared with HD." (PMID 34187852, 2021). "Fresh PBMC and tumor associated cells were isolated from a separate cohort of canine melanoma patients (P21-31) and tested by an abbreviated flow cytometry panel that included interrogation for CD3+ T cell subsets (CD4+, CD4-CD8-, and CD8+), FoxP3 and granzyme B." (PMID 34926643, 2021). "IHC analysis of melanoma tissues on CTL-related markers demonstrated that mice treated with OVA@SVMAV had the highest CTL infiltration level and protein levels of interferon-γ and granzyme B, which are two important proteins secreted by CTLs to eliminate tumor cells in the TME." (PMID 34452929, 2021). "Moreover, CY12-RP2 could inhibit melanoma lung metastasis, and abrogated the immunosuppressive effects of PDPN by increasing the proportion of CD3 + CD4 + T cells, CD3 + CD8 + T cells, CD49b + Granzyme B + NK cells, and CD11b + CD86 + M1-like macrophages and the levels of IL-1β, TNF-α, and IFN-γ." (PMID 38167452, 2024). "Leveraging The Cancer Genome Atlas (TCGA) datasets, we investigated NR4A1 expression in melanoma patients and identified a negative correlation between NR4A1 and genes involved in the antitumor immune responses, including IFNγ (interferon γ), GZMB (granzyme B), and PRF1 (perforin)." (PMID 38334978, 2024). "However, the CD8+ TIL in ADU-S100 + anti-PD-L1 vs. ADU-S100 only treated B16 melanomas expressed significantly higher levels of early activation marker CD69, consistent with their enhanced functional status, but they exhibited no significant changes in Granzyme B or PD1 expression." (PMID 38312842, 2024).